PPID (peptidylprolyl isomerase D)
Description:
PPIase that catalyzes the cis-trans isomerization of proline imidic peptide bonds in oligopeptides and may therefore assist protein folding. Proposed to act as a co-chaperone in HSP90 complexes such as in unligated steroid receptors heterocomplexes. Different co-chaperones seem to compete for association with HSP90 thus establishing distinct HSP90-co-chaperone-receptor complexes with the potential to exert tissue-specific receptor activity control. May have a preference for estrogen receptor complexes and is not found in glucocorticoid receptor complexes. May be involved in cytoplasmic dynein-dependent movement of the receptor from the cytoplasm to the nucleus. May regulate MYB by inhibiting its DNA-binding activity. Involved in regulation of AHR signaling by promoting the formation of the AHR:ARNT dimer; the function is independent of HSP90 but requires the chaperone activity. Involved in regulation of UV radiation-induced apoptosis. Promotes cell viability in anaplastic lymphoma kinase-positive anaplastic large-cell lymphoma (ALK+ ALCL) cell lines. (Microbial infection) May be involved in hepatitis C virus (HCV) replication and release.
Synonyms: CYP-40; CYPD
Tractability: Small molecule: a high-quality ligand is known; it belongs to a druggable protein family. PROTAC: ubiquitination databases record sites on it; its protein half-life has been measured; a small molecule that binds it is known.
Target class: Isomerase; Enzyme
Gene: Protein-coding gene on chromosome 4 (158,709,127 to 158,723,406, reverse strand). Ensembl gene ENSG00000171497.
Subcellular location: Cytoplasm; Nucleus, nucleolus; Nucleus, nucleoplasm
Subcellular location (Human Protein Atlas): Cytosol; Nucleoli; Nucleoli rim; Nucleoplasm; Primary cilium
Pathways (Reactome):
Signal Transduction: ESR-mediated signaling
Gene Ontology:
Molecular function: heat shock protein binding; Hsp90 protein binding; peptidyl-prolyl cis-trans isomerase activity; protein binding; transcription factor binding; cyclosporin A binding; Hsp70 protein binding; nuclear estrogen receptor binding
Biological process: cellular response to UV-A; lipid droplet organization; negative regulation of transcription by RNA polymerase II; positive regulation of apoptotic process; positive regulation of protein secretion; positive regulation of viral genome replication; protein folding; protein-containing complex assembly; viral release from host cell
Cellular component: cytoplasm; cytosol; nucleolus; nucleoplasm; nucleus
Genetic constraint (gnomAD): Loss-of-function variants: 38 observed, 38.22 expected, observed/expected ratio (o/e) 0.99, 90% interval 0.77 to 1.3. The upper end of that interval is the gene's LOEUF score, 1.3, which puts it in group 5 of 6, group 1 being the genes least tolerant of losing a copy. Missense variants: 367 observed, 389.12 expected, observed/expected ratio (o/e) 0.94, 90% interval 0.87 to 1.03. Synonymous variants: 148 observed, 135.29 expected, observed/expected ratio (o/e) 1.09, 90% interval 0.96 to 1.25.
Homologues: Orthologues: chimpanzee PPID (99% identical), macaque PPID (98% identical), mouse Ppid (94% identical), pig PPID (94% identical), rabbit PPID (93% identical), guinea pig PPID (92% identical), rat Ppid (86% identical), rat Ppidl1 (86% identical), dog PPID (83% identical), tropical clawed frog ppid (72% identical), zebrafish ppid (72% identical), Caenorhabditis elegans Y17G9B.4 (21% identical). Paralogues in human: NKTR (31% identical), PPIG (31% identical), PPIA (30% identical), PPIF (28% identical), PPIB (28% identical), PPIE (28% identical), PPIAL4C (27% identical), PPIAL4A (26% identical), PPIAL4D (26% identical), PPIAL4E (26% identical), PPIAL4F (26% identical), PPIAL4G (26% identical), and 10 more.
Diseases named in the same sentence as PPID in open-access papers:
PPID is named in the same sentence as 14 diseases in open-access papers, as found by Europe PMC text mining. Sharing a sentence is not in itself a finding about the gene and the disease. The quoted sentences say what the papers report.
Obesity (1 paper, 2016). Accumulation of substantial excess body fat. "Among these candidates, butyrylcholinesterase (Bche) and Sucrase-isomaltase (Si) peptidylprolyl isomerase D (PpiD) and electron-transferring-flavoprotein dehydrogenase (EtfdH) are all well-known for body weight or obesity." (PMID 27203862, 2016).
viral infection (1 paper, 2025). "Seven of these acetylated proteins, including DDX3X, PTBD, TRIM56, IPO7, PPID, SHMT2, and ZC3HAV1, have been implicated in innate immunity and viral infection, based on functional annotation using databases such as GO Biological Process, KEGG and reactome." (PMID 39747662, 2025).
tumor (5 papers, 2010 to 2025). "The up-regulation of PPID protein induced by oncogenic Ras through the Raf-1/MEK/ERK pathway has a decisive role in tumor progression." (PMID 37714937, 2023). "Furthermore, proteomic analysis revealed that BM@HA + NIR may induce necroptosis of tumor cells by activating peptidylprolyl isomerase D-related pathways." (PMID 40688054, 2025).
infection (4 papers, 2013 to 2024). The state of being infected such as from the introduction of a foreign agent such as serum, vaccine, antigenic substance or organism. "Host cells with the ppiD gene deleted showed partial reduction in the plating efficiency of T4, suggesting a supporting role of PpiD to improve the efficiency of the infection process." (PMID 33036312, 2020). "Some of them showed an amplification of the differential regulation during the time-course of WNV-infection (early vs. mock and late vs. early), such as PPID and PCM1 (down-regulated) and TAPBP and STAT1 (up-regulated)." (PMID 23874584, 2013).
PPID also shares sentences with these, for which no sentence is quoted: breast carcinoma (4 papers); prostate carcinoma (3); anaplastic large cell lymphoma (2); lymphoma (2); tauopathies (2); Azoospermia (1); cognitive decline (1); neurodegenerative disease (1); osteoporosis (1); T-cell lymphomas (1).